FOXP2 (forkhead box P2)
Diseases named in the same sentence as FOXP2 in open-access papers (continued):
Sharing a sentence is not in itself a finding about the gene and the disease.
infection (4 papers, 2016 to 2023). The state of being infected such as from the introduction of a foreign agent such as serum, vaccine, antigenic substance or organism. "The higher co-localization of TINs with FoxP2 versus DARPP32 is likely driven by the higher number of FoxP2+ neurons within the striatum as well as the sensitivity of DARPP32 expression/staining to disruption by infection or inflammation." (PMID 34106047, 2021). "Thus, injection of AAV-hSyn-FLEX-TVA-P2A-GFP-2A-oG in FoxP2-cre mice will permit subsequent infection of EnvA-ΔG- Rabies-mCherry) to selectively target ITCs and their presynaptic partners." (PMID 37775310, 2023).
neurodegenerative disease (4 papers, 2022 to 2025). A disorder of the central nervous system characterized by gradual and progressive loss of neural tissue and neurologic function. "The ‘Human UP’ genes include FOXP2, MTRNR2L8, DHX40, VPS13B, WDFY2 and PURB, all of which are associated with neurodevelopment or neurodegenerative disease." (PMID 36052683, 2022). "In addition to AD, note that Foxp2 is also integral to the development of a host of neurodegenerative diseases including FTD." (PMID 40979532, 2025).
genetic disorder (2 papers, 2016 to 2024). "This is true for groups with genetic disorders like children with mutations in FOXP2 and ZDHHC9; whilst there is a single causal gene, the cognitive and behavioural impairments associated with this mutation will impact upon cognitive development more broadly." (PMID 27747153, 2016).
psychiatric disorder (2 papers, 2022 to 2023). A disorder characterized by behavioral and/or psychological abnormalities, often accompanied by physical symptoms. "Notably, we found this relationship was notable only when the Foxp2-expressing neuron subtype was analyzed, highlighting the importance of using cell type–specific approaches in dissecting the molecular mechanism of complex psychiatric disorders." (PMID 35245111, 2022).
adenocarcinoma (1 paper, 2023). A common cancer characterized by the presence of malignant glandular cells. "Therefore, high EZH2 can indicate lower PRC2 function, and our mouse model and in vitro data show that one result of lowering PRC2 function in KRAS-driven adenocarcinomas is to de-repress FOXP2." (PMID 36670102, 2023).
hematological malignancies (1 paper, 2016). "There is currently little information regarding the biological roles of FOXP2 in normal B-cell differentiation or during the pathogenesis of hematological malignancies." (PMID 27224915, 2016).
lip (1 paper, 2024). "In addition, Foxp2 is linked to nonsyndromic cleft lip and/or palate through genome-wide linkage analysis." (PMID 38280850, 2024).
movement disorder (1 paper, 2024). Neurological conditions resulting in abnormal voluntary or involuntary movement, which may impact the speed, fluency, quality and ease of movement. "FOXP2 (Forkhead box P2, involved neuronal differentiation and movement disorders) was presented in both human glutamatergic and GABAergic neurons." (PMID 38289829, 2024).
FOXP2 also shares sentences with these, for which no sentence is quoted: Down syndrome (4 papers); epilepsy (3); Huntington disease (3); specific language impairment (3); colon cancer (2); communication disorder (2); deafness (2); immune disorders (2); neurological disorders (2); ovarian carcinoma (2); Rolandic epilepsy (2); acute lung injury (1); alopecia (1); ankyloglossia (1); Anxiety (1); Autoimmunity (1); B cell lymphomas (1); Bamforth-Lazarus syndrome (1); Blepharophimosis (1); Brain atrophy (1); brain malformation (1); Cerebellar atrophy (1); cerebellar disorder (1); congenital diaphragmatic hernia (1); COVID-19 (1); diarrhoea (1); duodenitis (1); endometrial cancer (1); Epicanthus inversus (1); gastritis (1).
A further 31 diseases each share a sentence with FOXP2 in 1 paper.